ENSG00000254536 (novel protein)
Gene: Protein-coding gene on chromosome 10 (133,380,017 to 133,420,271, forward strand). Ensembl gene ENSG00000254536.
Genetic constraint (gnomAD): Missense variants: 497 observed, 523.45 expected, observed/expected ratio (o/e) 0.95, 90% interval 0.88 to 1.02. Synonymous variants: 224 observed, 231.33 expected, observed/expected ratio (o/e) 0.97, 90% interval 0.87 to 1.08.